BMP4 (bone morphogenetic protein 4)
Diseases named in the same sentence as BMP4 in open-access papers (continued):
Sharing a sentence is not in itself a finding about the gene and the disease.
hemochromatosis (1 paper, 2024). A disorder of iron metabolism characterized by a triad of HEMOSIDEROSIS; LIVER CIRRHOSIS; and DIABETES MELLITUS. "We found one patient carrying the BMP4 p.R269Q variant among 54 primary iron overload patients and one patient harboring the BMP4 p.H251Y variant among 148 patients with secondary hemochromatosis." (PMID 39563390, 2024). "The cohort of Chinese patients with primary iron overload should be expanded in the future to analyze the role of the BMP4 p.H251Y and p.R269Q variants in hemochromatosis and obtain a more comprehensive understanding of the relevant pathological mechanisms." (PMID 39563390, 2024). "Currently, the BMP4 gene variants and pathogenesis in hemochromatosis are rarely studied." (PMID 39563390, 2024). "Therefore, it suggested that these two BMP4 variants may be hemochromatosis pathogenic." (PMID 39563390, 2024). "However, the role of BMP4 and BMP4 variants in hemochromatosis pathogenesis remains unclear." (PMID 39563390, 2024). "However, the pathogenicity of the BMP4 p.R269Q variant in hemochromatosis remains unknown." (PMID 39563390, 2024). "Our results indicated that the BMP4 p.H251Y and BMP4 p.R269Q variants in exon 4 of the BMP4 gene can downregulate hepcidin production by inhibiting the BMP/SMAD axis, suggesting their potential role in the pathogenesis of hemochromatosis." (PMID 39563390, 2024). "We also identified heterozygous p.R269Q and p.H251Y variants in exon 4 of the BMP4 gene in hemochromatosis patients without known HH-related gene variants." (PMID 39563390, 2024). "Our experimental results suggested that the BMP4 p.H251Y and p.R269Q variants decreased hepcidin levels via the downregulation of the BMP/SMAD signaling pathway, indicating that the BMP4 p.H251Y and p.R269Q variants may be novel pathogenic factors of hemochromatosis." (PMID 39563390, 2024).
Hirschsprung disease (1 paper, 2023). Hirschsprung disease (HSCR) is a congenital intestinal motility disorder that is characterized by signs of intestinal obstruction due to the presence of an aganglionic segment of variable extent in the terminal part of the colon. "Furthermore, the transcription factor Smad-interacting protein 1 (also known as SIP1 or ZEB2), a negative regulator of BMP4 signaling, is involved in the specification, differentiation, and migration of neural crest cells, and mutations in this gene are associated with Hirschsprung disease." (PMID 37958648, 2023).
hypercholesterolaemia (1 paper, 2020). "In conclusion, low WSS and hypercholesterolaemia induce a BMP4-HoxB9-TNF-NF-κB pathway that drives inflammation during early atherogenesis." (PMID 31504243, 2020). "Finally, we investigated whether the BMP4-HoxB9-TNF axis is potentially involved in atherogenesis by determining the effects of hypercholesterolaemia on the expression of components of this pathway." (PMID 31504243, 2020).
hyperthyroidism (1 paper, 2024). Overactivity of the thyroid gland resulting in overproduction of thyroid hormone and increased metabolic rate. "Thus, it seems possible that similar mechanisms (T3 → TRβ/RXRα → HLF → HIF-1α → EPO and T3 → SHH → BMP-4 → BFU-E) may lead to increased erythropoiesis in human and feline hyperthyroidism and may explain the presence of erythrocytosis observed in this disease." (PMID 39518858, 2024).
hypertrophic cardiomyopathy (1 paper, 2022). A condition in which the myocardium is hypertrophied without an obvious cause. "In addition, many genes with changes in both m6A modification and gene expression are related to cardiac processes, such as Myh7, bmp4 and Ttn, which were shown to be related to hypertrophic cardiomyopathy." (PMID 35953789, 2022).
interstitial nephritis (1 paper, 2020). Inflammation of the renal tubules and supporting tissues of the kidney. "Additionally, in a model of interstitial nephritis, induced inactivation of the ALK3 receptor (a high-affinity receptor for BMP2 and BMP4) sensitizes proximal tubule cells to injury and promotes fibrosis." (PMID 33328501, 2020).
iron overload (1 paper, 2024). "Our study aimed to explore the pathogenicity and underlying mechanism of BMP4 p.H251Y and BMP4 p.R269Q variants in patients with iron overload." (PMID 39563390, 2024). "Sanger sequencing was conducted to identify the novel variants in the BMP4 gene of patients with unexplained iron overload." (PMID 39563390, 2024). "Then we performed Sanger sequencing for BMP4 in 54 primary iron overload patients and 148 patients with secondary iron overload." (PMID 39563390, 2024). "The BMP4 p.H251Y and p.R269Q variants can downregulate hepcidin levels by inhibiting the BMP/SMAD axis, suggesting they may play pathogenic roles in iron overload." (PMID 39563390, 2024).
Kapur-Toriello syndrome (1 paper, 2023). Kapur-Toriello syndrome is an extremely rare syndrome characterized by facial dysmorphism, severe intellectual deficiency, cardiac and intestinal anomalies, and growth retardation. "A deep intronic, de novo variant, c.370 + 441G > A, was found in a highly conserved region of BMP4 in a patient with Kapur-Toriello syndrome." (PMID 37946251, 2023). "The phenotypic spectrum of one gene, RMND1, was expanded to include polymicrogyria, whilst BMP4 is being investigated as a candidate for Kapur-Toriello syndrome." (PMID 37946251, 2023).
keratoconus (1 paper, 2009). A degenerative, structural disorder of the eye, characterized by a cone-shaped protrusion of the cornea. "From the higher expression of BMP4 in keratoconus in this study, it was suggested that BMP4 might play an important role in mediating the apoptosis of keratocytes in keratoconus." (PMID 19956410, 2009). "We found that BMP4 was expressed significantly more highly in keratoconus than in normal corneas." (PMID 19956410, 2009). "However, we assessed the expression of eight genes in more detail by employing RT-PCR and real-time PCR, which confirmed the overexpression of BMP4, CFL1, and MRVI1, and the underexpression of ACTA2, GRCC10, TIMP3, TIMP1, and SSTR1 in keratoconus." (PMID 19956410, 2009).
Lewis lung carcinoma (1 paper, 2019). "It binds to BMP4 and in xenograft mice models of Lewis lung carcinoma cells, Olfml3 was expressed in tumor endothelial cells and pericytes." (PMID 31083655, 2019).
lichen planus (1 paper, 2008). A chronic, recurrent, pruritic inflammatory disorder of unknown etiology that affects the skin and mucus membranes. "First, BMP-4 is upregulated in the epithelium of lichen planus." (PMID 18813341, 2008).
Lissencephaly (1 paper, 2019). A spectrum of malformations of cortical development caused by insufficient neuronal migration that subsumes the terms agyria, pachygyria and subcortical band heterotopia. "Importantly, rescue of the DMe patterning in Lmx1a−/−;b−/− mutants by early electroporation of Bmp4 into the DMe was sufficient to normalize activity of the Wnt-β-catenin signaling in the distantly located neocortex to restore lissencephaly." (PMID 31729356, 2019).
liver disease (1 paper, 2014). "To determine the effect of liver disease on BMP4 expression we assessed mRNA and protein expression in tissue from age-matched organ donors and patients with HCV infection or alcohol-related liver disease (ALD)." (PMID 23775568, 2014).
low grade glioma (1 paper, 2020). A grade I or grade II glioma arising from the central nervous system. "The results showed that low-grade gliomas (LGG) express higher BMP4 levels and exhibit lower mortality rates than HGGs that express lower levels of BMP4." (PMID 32102285, 2020).
male infertility (1 paper, 2022). The inability of the male to effect fertilization of an ovum after a specified period of unprotected intercourse. "BMP4 is a member of TGFβ family and it exerts a major influence male fertility since knockdown of BMP4 caused male infertility in mice." (PMID 36513649, 2022).
memory impairment (1 paper, 2021). "We found that the middle-aged BMP4 transgenic mice exhibited memory impairment via the Morris water maze experiment." (PMID 33723239, 2021). "This study used a conditional BMP4 transgenic mouse model and found that BMP4 overexpression led to memory impairment in mice." (PMID 33723239, 2021).
mesangial sclerosis (1 paper, 2018). "Podocyte-specific Bmp4 tgm showed typical mesangial sclerosis accompanied by podocyte loss and increased phosphorylated Smad1 levels in mesangial cells." (PMID 30158674, 2018). "Thus, podocyte loss itself is responsible for mesangial sclerosis, and the increased BMP4 expression observed in podocytes induces Smad1 activation in mesangial cells in a paracrine fashion." (PMID 30158674, 2018).
Miscarriage (1 paper, 2023). A pregnancy that ends at a stage in which the fetus is incapable of surviving on its own, defined as the spontaneous loss of a fetus before the 22th week of pregnancy. "The aberrant expression of BMP4 was associated with miscarriages in G1." (PMID 36768749, 2023).
myocarditis (1 paper, 2024). Myocarditis is a condition that is characterized by inflammation of the heart muscle (myocardium). "Cardiac BMP pathway dysregulation was reflected by reduced BMP4 serum concentration in patients with myocarditis." (PMID 39196111, 2024). "We found significantly reduced BMP4 serum concentration in patients with myocarditis in comparison to age-matched healthy volunteers." (PMID 39196111, 2024). "Moreover, the receiver operating characteristic (ROC) curve of BMP4 serum concentration indicated high sensitivity and specificity, highlighting that reduced BMP4 production is a major trait of perturbed myocardial homeostasis and a potential biomarker for the diagnosis in human myocarditis." (PMID 39196111, 2024).
myxomatous mitral valve prolapse (1 paper, 2015). "BMP4 was involved in valvular interstitial cell activation in human myxomatous mitral valve prolapse." (PMID 25591903, 2015).
Nicotine addiction (1 paper, 2025). "Among these, the TGF-beta signaling pathway, T cell receptor signaling pathway, and Nicotine addiction pathway were highly enriched (p < 0.01) enriched involving relevant genes (PITX2, ID4, BMP4, DLG1, IKBKB, ICOS, GRIA3, and SLC17A6)." (PMID 40496916, 2025).
ocular hypertension (1 paper, 2012). Abnormally high intraocular pressure. "The contribution of common genetic variation at the FOXC1, TGFβ2, and BMP4 loci to risk of POAG was investigated in a case-control association study in 330 British Caucasian individuals comprised of 272 high-tension glaucoma (HTG) and 58 ocular hypertension (OHT), and 276 matched controls." (PMID 22736943, 2012).
odontogenic cyst (1 paper, 2018). A cyst in the jaw that arises from tissues of tooth development. "In conclusion, the results suggest that BMP4 and FGF8 are expressed in different odontogenic cyst and tumors with varying intensity based on their expected behavior." (PMID 30079292, 2018).
orofacial cleft 11 (1 paper, 2009). Any orofacial cleft in which the cause of the disease is a mutation in the BMP4 gene. "On the other hand, three missense mutations in BMP4 were reported in patients with orofacial cleft 11 (OMIM 600625)." (PMID 20057906, 2009).
Osteoblastoma (1 paper, 2013). A rare benign bone-forming neoplasm usually arising from the spine. "Indeed, Wnt/beta-catenin target genes involved in bone metabolism, such as BMP2, BMP4, PTGS2 and MMP16, showed high expression levels in osteoblastoma." (PMID 24236197, 2013).
osteomyelitis (1 paper, 2024). An acute or chronic inflammation of the bone and its structures due to infection with pyogenic bacteria. "Notably, BMP4 levels were downregulated in the mouse model of osteomyelitis when treated with EZM0414." (PMID 38830934, 2024).
pancreatic adenocarcinoma (1 paper, 2025). "Bone Morphogenetic Protein 4 (BMP4) plays a critical role in development, but its function in pancreatic adenocarcinoma (PAAD) is not well understood." (PMID 41169612, 2025).
pancreatic diseases (1 paper, 2011). "These mouse models represent useful tools for toxicological screening, and for investigating the mechanisms responsible for pancreatic Bmp4 functions in vivo, with relevance to improving our understanding of pancreatic diseases." (PMID 21949805, 2011).
Peritoneal Fibrosis (1 paper, 2018). Disorder characterized by a wide range of structural changes in PERITONEUM, resulting from fibrogenic or inflammatory processes. "Another approach, however, based on the findings from the current study, would be to focus on introducing BMP4 and IGFBP4 to prevent MMT and peritoneal fibrosis." (PMID 29774544, 2018). "In a mouse model of peritoneal fibrosis induced by intraperitoneal TGF‐β1‐expressing adenovirus, there was attenuation of BMP4 immunostaining of the surface of the peritoneum." (PMID 29774544, 2018). "Moreover, we found that BMP4 immunostaining on peritoneal surfaces was attenuated versus healthy controls in human peritoneal dialysis tissue and in a mouse model of TGF‐β1‐induced peritoneal fibrosis." (PMID 29774544, 2018).
placental diseases (1 paper, 2020). "Furthermore, these results provide an evidence of feasibility of using BMP4 derived trophoblast cells in understanding of early human embryogenesis and placental diseases." (PMID 32814763, 2020).
polyarticular JIA (1 paper, 2024). "In this study, we show that methotrexate can effectively decrease BMP4, a member of the TGFβ superfamily, protein expression in FLS from persistent, ETB, and polyarticular JIA." (PMID 38166938, 2024).
postmenopausal osteoporosis (1 paper, 2024). Metabolic disorder associated with fractures of the femoral neck, vertebrae, and distal forearm. "MEG3 has been demonstrated to upregulate miR-133a-3p and inhibit osteogenic differentiation in bone marrow MSCs from patients with postmenopausal osteoporosis, which also plays an essential role in osteogenic differentiation in bone marrow MSCs, partially by activating BMP4 transcription." (PMID 39628661, 2024).
Pulmonary hypoplasia (1 paper, 2014). "Using an ovine CDH model, in conjunction with pulmonary hypoplasia, we report a reduced expression of Wnt2, BMP4, and LGL1, key players in promoting proximal-distal patterning, branching morphogenesis, and regulating alveolization." (PMID 25593968, 2014). "We have shown that molecular markers of both early (BMP4) and late (LGL1) lung development are down regulated, in association with pulmonary hypoplasia at term." (PMID 25593968, 2014). "Therefore, it appears that the mechanical compression of herniated viscera on the developing lungs results in the persistent down regulation of BMP4 and LGL1, which results in pulmonary hypoplasia." (PMID 25593968, 2014).
refractive error (1 paper, 2022). A defect in the focusing of light on the retina as in astigmatism, myopia, or hyperopia. "The discovery of two independently associated variants in the PRSS56, BMP4 and SIX6 genes provided additional evidence that these genes play a role in the development of refractive errors." (PMID 35022715, 2022).
respiratory failure (1 paper, 2021). The significant impairment of gas exchange within the lungs resulting in hypoxia, hypercarbia, or both, to the extent that organ tissue perfusion is severely compromised. "As an antagonist of the BMP4 signaling pathway, FSTL1 plays a crucial part in the embryogenesis of lung and alveolar, thus FSTL1−/− mice showed postnatal lethality due to respiratory failure." (PMID 33509151, 2021).
retinal detachment (1 paper, 2019). An eye emergency condition which may lead to blindness if left untreated. "The interaction between BMP4 and TGFβ1 may be important in its role in pathogenesis of retinal detachment." (PMID 30568244, 2019).
sarcoma (1 paper, 2025). A usually aggressive malignant neoplasm of the soft tissue or bone. "In contrast, BMP4 methylation was hazardous for the DSS of MESO and PCPG, PFS of PRAD, and DFS of sarcoma (SARC)." (PMID 41169612, 2025).
seminoma (1 paper, 2023). A radiosensitive malignant germ cell tumor found in the testis (especially undescended), and extragonadal sites (anterior mediastinum and pineal gland). "This study reports the effects of activin A and BMP4 on the gene expression profiles of TCam-2 (representing seminoma cells) and NT2/D1 (representing non-seminoma cell type) cell lines and provides evidence that IPO5 may be important to selectively mediate BMP signals." (PMID 37048077, 2023).
silicosis (1 paper, 2021). Silicosis is a respiratory disease caused by breathing in (inhaling) silica dust. "This study revealed that BMP4 was a differential gene hub in PBMCs from patients with silicosis." (PMID 34517882, 2021). "The results indicated that the expression of SMAD2, MAPK3, THBS1, ITGB3, and BMP4 was increased, while the expression of SMAD3 and CD44 was significantly low expression in PBMCs from patients with silicosis, indicating consistent results with the RNA-Seq data." (PMID 34517882, 2021). "Next, it was confirmed that gene expression of BMP4 and MAPK3 were higher in PBMCs from patients with silicosis." (PMID 34517882, 2021). "To date, BMP4 in the BMP protein family has not been reported in silicosis." (PMID 34517882, 2021).
sirenomelia (1 paper, 2012). Sirenomelia is a rare, genetic, developmental defect during embryogenesis disorder characterized by fusion of the lower limbs and associated with some degree of lower extremity reduction and persistent vitelline artery. "The decrease of Tbx4 expression in the hindlimb bud by defective BMP4 signaling could be a one of the causative factors for the defective skeletal elements in sirenomelia." (PMID 23028455, 2012). "Isl1Cre;Bmp4flox/flox (hereafter designated as Bmp4 cKO) mutants possess hindlimb fusion similar to sirenomelia in humans." (PMID 23028455, 2012). "Indeed, loss of a single copy of Bmp4 and both copies of Bmp7 in Bmp4flox/+Bmp7flox/flox compound mutant mice (Hoxa3-Cre;Bmp4flox/+Bmp7flox/flox) resulted in hindlimb fusion as well as loss of the bladder and anal stenosis, essential diagnotic features of sirenomelia (n = 3)." (PMID 23028455, 2012). "Taken together, Bmp4 cKO mouse is a useful model to elucidate not only pathogenesis of sirenomelia but also to understand the developmental mechanisms of coordinated caudal embryonic formation." (PMID 23028455, 2012). "These Bmp4 conditional KO mice showed sirenomelia phenotypes including hindlimb fusion and also hitherto undescribed lethal pelvic/urogenital organ dysplasia." (PMID 23028455, 2012). "We have identified Bmp4 cKO mice as a new mouse model for sirenomelia." (PMID 23028455, 2012).
spinal tuberculosis (1 paper, 2022). "The severity of spinal tuberculosis had been reported to be associated with vitamin D receptor (VDR), osteopontin (OPN), and bone morphogenetic protein-4 (BMP-4) gene polymorphism." (PMID 35633888, 2022).
Splenomegaly (1 paper, 2024). Abnormal increased size of the spleen. "Enforced expression of BMP4 in the NonSil tumors led to a systemic reduction in metastasis in other tumor models, and was associated with a reduction in tumor-induced splenomegaly." (PMID 38689334, 2024).
spondylolisthesis (1 paper, 2025). A condition in which there is forward displacement of a vertebral bone over the on below it. "The predominant NPPCs in C2 exhibit osteogenic features, with high expression of genes such as BMP4, TGFB2, and THBS1, indicating an adaptive response to spinal instability, which is often linked with spondylolisthesis." (PMID 40883814, 2025).
steatosis (1 paper, 2019). Increased lipid within the cytoplasm of cells. "Here, we found that BMP4 was up-regulated in oleic acid-induced steatosis and during the development of high fat diet (HFD)-induced NAFLD." (PMID 31831718, 2019).